RN7SL557P (RNA, 7SL, cytoplasmic 557, pseudogene)
Gene: Miscellaneous RNA gene on chromosome 16 (25,185,253 to 25,185,538, reverse strand). Ensembl gene ENSG00000266166.
Homologues: Paralogues in human: RN7SL163P (66% identical), RN7SL811P (61% identical), RN7SL693P (60% identical), Metazoa_SRP (59% identical), RN7SL48P (59% identical), RN7SL460P (58% identical), Metazoa_SRP (57% identical), RN7SL154P (57% identical), RN7SL391P (57% identical), RN7SL785P (56% identical), Metazoa_SRP (56% identical), RN7SL134P (56% identical), and 699 more.